TFPI2 (tissue factor pathway inhibitor 2)
Diseases named in the same sentence as TFPI2 in open-access papers (continued):
Sharing a sentence is not in itself a finding about the gene and the disease.
nasopharyngeal carcinoma (4 papers, 2010 to 2025). A carcinoma arising from the nasopharyngeal epithelium. "It is observed that the TFPI-2 expression, decreasing or even diminishing, attributed to promoting hypermethylation in nasopharyngeal carcinoma." (PMID 22208663, 2012). "In this study, we investigated whether TFPI-2 was inactivated epigenetically in nasopharyngeal carcinoma (NPC)." (PMID 21062455, 2010). "In nasopharyngeal carcinoma (NPC) cells, TFPI2 overexpression and a combination of cisplatin treatment were found to elicit a synergistic effect on promoting apoptosis and antitumor activity compared to cisplatin or TFPI2 treatment alone." (PMID 40765823, 2025). "Our study demonstrates that FA-MNP/CDDP/TFPI-2, containing both CDDP and TFPI-2, was been successfully synthesized and can efficiently inhibit the growth of nasopharyngeal cancer cells both in vitro and in vivo." (PMID 33967612, 2021).
ovarian clear cell cancer (4 papers, 2021 to 2025). An invasive malignant neoplasm that arises from the ovary and is characterized by a predominance of clear and hobnail malignant epithelial cells. "Interestingly, in opposition to other tumours, TFPI2 is often overexpressed in ovarian clear cell carcinoma (the EOC subtype most associated with VTE), though its precise role and the underlying mechanisms remain unclear." (PMID 38203310, 2023). "Overall, TFPI2 expression is highly specific for ovarian clear cell carcinoma, but its specificity in endometrial and renal cell carcinomas remains unclear." (PMID 40361374, 2025). "In ovarian clear cell carcinoma, TFPI2 overexpression may contribute to VTE pathogenesis." (PMID 40361374, 2025). "Tissue factor pathway inhibitor 2 (TFPI2) is a novel serum biomarker that discriminates ovarian clear cell carcinoma (CCC) from borderline ovarian tumors (BOTs) and non-clear cell epithelial ovarian cancers (EOCs)." (PMID 34009487, 2021).
pancreatic adenocarcinoma (4 papers, 2016 to 2023). "Hypermethylation of SFRP1, BNC1, and TFPI2 were in the univariate screening associated with poor survival for stage IV pancreatic adenocarcinoma." (PMID 29212200, 2017). "Initially, analysis of pancreatic adenocarcinoma TCGA data confirmed that the methylation levels of BMP3, NPTX2, SPARC, SFRP1 and TFPI2 genes were significantly higher in tumor compared with normal tissue, reinforcing their potential as useful biomarkers." (PMID 37481552, 2023). "We developed a diagnostic prediction model (age >65, BMP3, RASSF1A, BNC1, MESTv2, TFPI2, APC, SFRP1 and SFRP2), which was able to differentiate between pancreatic adenocarcinoma and a large control group of great clinical relevance." (PMID 27891190, 2016). "A panel of hypermethylated genes (BMP3, RASSF1A, BNC1, MESTv2, TFPI2, APC, SFRP1 and SFRP2) are able to differentiate between patients with pancreatic adenocarcinoma and a most relevant control group." (PMID 27891190, 2016).
breast tumor (3 papers, 2013 to 2021). "We found that TFPI-2 staining was observed mainly on the cytoplasm of cells in breast glandular tissue or breast tumor tissue." (PMID 23497249, 2013). "Immunohistochemical staining combined with digital image analysis was used to quantify the expression of TFPI-2 protein in breast tumor tissues." (PMID 23497249, 2013). "In vivo subcutaneous xenotransplanted tumor model also revealed that over-expression of TFPI2 could suppress breast tumor growth via down-regulation of TWIST1-mediated integrin α5 expression." (PMID 32248791, 2020).
colorectal tumor (3 papers, 2013 to 2021). "Furthermore, we detected LCT13 transcripts in 56% of colorectal tumours exhibiting reduced TFPI-2 expression." (PMID 23703216, 2013). "The methylation level of TFPI2 in colorectal tumor tissues was significantly higher than that in colorectal normal tissues (26.930% versus 0.002%, P < 0.00001)." (PMID 29137404, 2017).
diabetes (3 papers, 2016 to 2025). "Further investigation revealed that PROM1, TFPI2, and PFKFB3 are crucial genes involved in the regulation of IL11 expression in patients with kidney stones and diabetes." (PMID 37480086, 2023). "Beyond oncology, TFPI2 is expressed by inflammatory and endothelial cells and plays roles in non-neoplastic diseases such as diabetes and pregnancy-induced hypertension." (PMID 40361374, 2025).
diabetic nephropathy (3 papers, 2023 to 2025). "In diabetic nephropathy, TFPI2 expression is upregulated in the renal cortex of affected mice, where it inhibits VSMC proliferation and migration, thus limiting intimal hyperplasia under diabetic conditions." (PMID 40361374, 2025). "However, contradictory evidence indicates that in diabetic nephropathy, TFPI2 may promote endothelial-to-mesenchymal transition via TGF-β2/Smad signaling, contributing to renal fibrosis and disease progression." (PMID 40361374, 2025).
liver cancer (3 papers, 2022 to 2025). An epithelial or non-epithelial malignant neoplasm that arises from the liver. "In vivo, TFPI2 overexpression decreased tumor volume in an orthotopic nude mouse liver cancer model, but GADD45A knockdown reversed this effect." (PMID 40765823, 2025). "To examine the effect of TFPI2 on HCC, we first detected the expression of TFPI2 in different liver cancer cells." (PMID 40765823, 2025). "In vivo, TFPI2 overexpression decreased tumor volume in an orthotopic nude mouse liver cancer model, but CCAR2 knockdown reversed this effect." (PMID 40765823, 2025). "MBD3 has been demonstrated to promote the metastasis and growth of various digestive tract tumors, and, in liver cancer, it can enhance the growth, angiogenesis, and metastasis of tumor cells by inhibiting the tissue factor pathway inhibitor 2 (TFPI2)." (PMID 37370795, 2023). "Additionally, immunofluorescence co-localization showed that TFPI2, CCAR2, and BRCC3 had clear co-localization in liver cancer cells." (PMID 40765823, 2025). "Since DDX17 is a significant transcription factor in liver cancer, we speculated whether DDX17 can regulate TFPI2 expression." (PMID 40765823, 2025). "However, the potential role of TFPI2 in modulating HCC drug sensitivity remains poorly characterized, representing a critical knowledge gap in liver cancer therapeutics." (PMID 40765823, 2025). "In liver cancer, MBD3 has been shown to promote tumor cell growth, angiogenesis, and metastasis by inhibiting the tumor suppressor tissue factor pathway inhibitor 2 (TFPI2)." (PMID 37370795, 2023).
metastatic cancer (3 papers, 2014 to 2025). A carcinoma which has spread from the original site of growth to another anatomic site. "Hypermethylation of the TFPI-2 gene promoter was higher in metastatic cancer in contrast to localized tumors and under-expression of TFPI-2 was linked to poor prognosis and metastasis." (PMID 39153052, 2024). "Regarding its regulation, epigenetic silencing has been frequently described in metastatic cancers compared to localized tumors, and suppression of the ERK and AKT pathways contributes to the Tfpi2-mediated proliferation inhibition." (PMID 39859313, 2025). "This appears to be the case for Tissue Factor Pathway Inhibitor 2 (TFPI2), as methylated, and silenced TFPI2 DNA is used as a biomarker for metastatic cancer." (PMID 24489651, 2014).
ovarian tumor (3 papers, 2016 to 2024). "The second limitation is that we have not identified the mechanism underlying the high level of serum TFPI2 in patients with ovarian tumors other than CCC." (PMID 34009487, 2021). "Currently, the expression pattern of TFPI2 in the more aggressive ovarian tumours is unclear when considering all histological subtypes." (PMID 39199316, 2024). "Furthermore, we consider that CA125, TFPI2, and imaging parameters obtained from ultrasound and MRI may be useful for more precise prediction of ovarian tumor types." (PMID 34009487, 2021).
renal cell carcinoma (3 papers, 2020 to 2025). "Elevated circulating TFPI2 levels correlate with increased cancer aggressiveness and poor prognosis in ovarian, endometrial, and renal cell carcinoma, though the mechanisms underlying its tumor-promoting effects remain unclear." (PMID 40361374, 2025). "Recent studies have provided more detailed immunohistochemical analyses of TFPI2 expression in ovarian, endometrial, and renal cell carcinoma tissues." (PMID 40361374, 2025). "EGCG re-expresses several transcriptionally silenced genes via inhibiting DNMT1 activity, decreases growth, induces apoptosis in renal cell carcinoma by the re-expression of tissue factor pathway inhibitor-2 (TFPI-2), and decreases promoter hypermethylation." (PMID 36232603, 2022).
Sepsis (3 papers, 2014 to 2018). Sepsis is defined as life-threatening organ dysfunction caused by a dysregulated host response to infection. "TFPI-2 is mainly expressed in brain, spleen and lung during sepsis and LPS-induced systemic inflammation in mice (C57BL/6)." (PMID 30254643, 2018). "We further studied the theraputic potential of one selected TFPI-2 derived peptide (mouse) in a murine sepsis model." (PMID 27349742, 2016). "Recently, heparanase inhibitory peptides derived of TFPI-2 were demonstrated by us to inhibit heparanase procoagulant activity and attenuate sepsis in mouse models." (PMID 25386347, 2014).
small cell lung carcinoma (3 papers, 2019 to 2025). Small cell lung cancer (SCLC) is a highly aggressive malignant neoplasm, accounting for 10-15% of lung cancer cases, characterized byrapid growth, and early metastasis. "LSD1 inhibition restores TFPI2 in triple-negative breast cancer, and LSD2 knockdown increases TFPI2 in small cell lung cancer." (PMID 40361374, 2025). "In gefitinib-tolerant human small-cell lung cancer PC9 cells, KDM5A specifically inhibits the proliferation drug-tolerant cells without affecting their parent cells via suppressing the expression of tissue factor pathway inhibitor 2 (TFPI2)." (PMID 33596982, 2021).
B-cell lymphoma (2 papers, 2020 to 2023). "For example, tissue factor pathway inhibitor-2 (TFPI-2) is hypermethylated in its promoter region, decreasing its expression, and death-associated protein kinase (DAPK) hypermethylation has been correlated to negative prognosis in canine B-cell lymphoma." (PMID 36766357, 2023).
benign ovarian tumors (2 papers, 2016 to 2025). "These AUC values of TFPI2 were also higher than those of CA125 in distinguishing all EOC patients (including CCC patients) from patients with benign ovarian tumors (AUC = 0.814)." (PMID 27798689, 2016). "We provide clinical evidence that serum TFPI2 can discriminate patients with CCC from patients with ovarian benign tumors, as well as other EOC subtypes." (PMID 27798689, 2016). "There were no trends common between the training and validation sets for effect of age on serum TFPI2 level when each group (benign ovarian tumors, CCC and non-CCC EOCs) was considered." (PMID 27798689, 2016). "Serum TFPI2 levels were also significantly higher in CCC patients than in patients over 50 years old with benign ovarian tumors (data not shown)." (PMID 27798689, 2016).
brain tumor (2 papers, 2024 to 2026). "In experimental models of highly invasive human GBM, TFPI-2 was undetectable, in contrast to normal expression in healthy brain and lower-grade brain tumors." (PMID 39153052, 2024). "Similarly, in GBM, high-methylated TFPI-2 contributed to the aggressive phenotype of brain tumor cells and might constitute a negative prognostic marker." (PMID 39153052, 2024).
cervical neoplasms (2 papers, 2012 to 2020). "Gene expression of TFPI2 was decreased in samples of bladder tumors and cervical tumors, while TFPI2 protein concentrations in serum were higher in ovarian clear cell adenocarcinoma patients." (PMID 33381488, 2020).
clear cell carcinoma (2 papers, 2021 to 2025). "A previous study used conditioned media (secretome) from clear cell carcinoma cell lines and other types of EOCs to identify tissue factor pathway inhibitor 2 (TFPI2) as a potential diagnostic marker for differential diagnosis." (PMID 34680597, 2021). "Although miRNA and lncRNA regulation of TFPI2 in ovarian, endometrial, and renal clear cell carcinomas remains underexplored, their expression influences the biology of clear cell carcinomas and their potential as biomarkers." (PMID 40361374, 2025). "In fact, clear cell carcinomas—ovarian, endometrial, and renal—exhibit high TFPI2 and M2 TAM infiltration." (PMID 40361374, 2025). "Additionally, we reassess TFPI2′s role in tumorigenesis, particularly in clear cell carcinoma, as well as in chronic inflammation." (PMID 40361374, 2025).
coronary atherosclerosis (2 papers, 2015 to 2017). Atherosclerosis of the coronary vasculature. "These analyses revealed that there were statistically significant associations between TFPI-2 gene polymorphisms and coronary atherosclerosis." (PMID 26496276, 2015). "In summary, this is the first such study that shows TFPI-2 gene polymorphisms have an influence on developing coronary atherosclerosis." (PMID 26496276, 2015). "In this study, we aimed to investigate the association between TFPI-2 gene polymorphisms and coronary atherosclerosis." (PMID 26496276, 2015). "It was strengthened that TFPI-2 gene polymorphisms were associated with coronary atherosclerosis." (PMID 26496276, 2015). "The mechanism for the regulation of TFPI-2 gene polymorphisms in coronary atherosclerosis is still unknown." (PMID 26496276, 2015). "Therefore, we performed a detailed study to evaluate the association between TFPI-2 gene polymorphism and the development of coronary atherosclerosis." (PMID 26496276, 2015). "However, in patients with coronary atherosclerosis, TFPI-2 gene polymorphisms might not predict the severity of coronary atherosclerosis or the occurrence of CVE." (PMID 26496276, 2015). "Moreover, TFPI-2 gene polymorphisms might not predict the severity of coronary atherosclerosis." (PMID 28716011, 2017).
diffuse large B-cell lymphoma (2 papers, 2014 to 2017). "In the present study TFPI-2 methylation and gene expression have been investigated in canine Diffuse Large B-cell lymphomas (cDLBCL)." (PMID 24695110, 2014). "In the previous study, TFPI2 methylation could reduce expression in canine Diffuse Large B-cell lymphomas and esophageal squamous cell carcinoma." (PMID 29137404, 2017).
endometriosis (2 papers, 2016 to 2021). The growth of functional endometrial tissue in anatomic sites outside the uterine body. "TFPI2 showed good performance in discriminating stage II–IV CCC from BOTs and other EOCs (AUC 0.815 for TFPI2 versus 0.505 for CA125) or endometriosis (AUC 0.957 for TFPI2 versus 0.748 for CA125)." (PMID 34009487, 2021). "We speculate that careful monitoring of both CA125 and TFPI2 may lead to early detection of transformation from endometriosis to ovarian CCC over time in patients with endometriosis." (PMID 34009487, 2021). "Among the 77 patients with benign ovarian lesions, only one patient with benign serous adenoma, who had a complication of chronic renal dysfunction (serum creatinine: 2.2 mg/dl), showed a positive result for TFPI2, but all patients with endometriosis (n = 21) were below the cutoff level." (PMID 34009487, 2021). "TFPI2, which completely discriminated CCC from endometriosis in contrast to CA125, may work when both serum markers are evaluated together." (PMID 34009487, 2021). "Applying a cut-off value of 280 pg/mL, TFPI2 could distinguish early-stage (FIGO I and II) CCC from endometriosis with 72.2% sensitivity, 93.3% specificity, and 88.8% accuracy." (PMID 27798689, 2016). "Additionally, TFPI2 (AUC = 0.855, 95% CI 0.778–0.933) was superior to CA125 (AUC = 0.520, 95% CI 0.392–0.650) in discrimination of CCC patients, even at stage I (AUC of TFPI2: 0.811; AUC of CA125: 0.579), from endometriosis patients." (PMID 34009487, 2021). "Unlike CA125, which was also elevated in patients with endometriosis and several EOC subtypes, serum TFPI2 levels were specifically elevated only in ovarian CCC patients, consistent with the mRNA expression pattern in tumor tissues." (PMID 27798689, 2016).
gastric tumor (2 papers, 2014 to 2020). "The TFPI2 methylation levels were assessed in gastric tumors compared with corresponding normal margins, which showed TFPI2 hyper methylation in majority of GC tissues." (PMID 32467737, 2020). "The results of the present study indicate that TFPI-2 expression was inhibited in the gastric tumor and peritumoral tissues, suggesting that the inhibition of TFPI-2 expression may decrease the stability of the extracellular matrix." (PMID 24396436, 2014).
Hepatitis (2 papers, 2020 to 2024). Inflammation of the liver. "The role of TFPI2, especially in inflammatory responses, involves its participation in LPS-induced liver inflammation in mice." (PMID 39617791, 2024). "For instance, the promoter methylation status of two factors, TFPI2 and IGFBP7, in serum is markedly higher than that in normal subjects and hepatitis patients and may thereby become a non-invasive molecular biomarker for the early diagnosis of HCC in the clinic." (PMID 32831081, 2020).
infarction (2 papers, 2023 to 2025). A localised pathological necrosis of tissue resulting from obstruction of the blood supply usually by a thrombus, an embolus, or vascular torsion. "Additionally, TFPI2 promotes M2 macrophage polarization via PPARγ activation and attenuates fibroblast activation, thereby facilitating myocardial repair post-infarction in diabetic models." (PMID 40361374, 2025).
ischemia (2 papers, 2022 to 2024). A hypoperfusion of the BLOOD through an organ or tissue caused by a PATHOLOGIC CONSTRICTION or obstruction of its BLOOD VESSELS, or an absence of BLOOD CIRCULATION. "Our study further highlights the MEG8/TFPI2 axis as potential therapeutic approach to improve angiogenesis in ischemia." (PMID 35039572, 2022). "We conclude that regulation of TFPI2 by MEG8 occurs both under basal conditions in the endothelium as well as during ischemia." (PMID 35039572, 2022). "Our study highlights the MEG8/TFPI2 axis as potential therapeutic approach to improve angiogenesis following ischemia." (PMID 35039572, 2022).
kidney clear cell carcinoma (2 papers, 2022 to 2025). "Analysis of The Cancer Genome Atlas (TCGA) kidney clear cell carcinoma (KIRC) database for RNA sequencing data related to ccRCC showed significantly reduced overall survival in high expressers of CXCL8 (IL8), CCL5, CSF2, TFPI-2, and SERPINE1 (PAI1)." (PMID 35886951, 2022).
myocardial infarction (2 papers, 2023 to 2025). Gross necrosis of the myocardium, as a result of interruption of the blood supply to the area, as in coronary thrombosis. "Through PPARγ activation, TFPI2 fosters M2 polarization and mitigates vascular injury following myocardial infarction." (PMID 40361374, 2025).
ovarian clear cell adenocarcinoma (2 papers, 2020). A malignant glandular epithelial neoplasm characterized by the presence of clear and hobnail cells. "TFPI2 is a serum biomarker for the detection of ovarian clear cell adenocarcinoma, and its predictive values are superior to that of CA125." (PMID 32208363, 2020).
renal carcinoma (2 papers, 2023 to 2025). A carcinoma arising from the epithelium of the renal parenchyma or the renal pelvis. "Overall, serum TFPI2 levels are upregulated in ovarian, endometrial, and renal cancer, with elevated serum levels linked to poor prognosis." (PMID 40361374, 2025). "TFPI2 has also been detected in tumor-infiltrating macrophages in gastric and renal carcinoma tissues." (PMID 40361374, 2025). "EGCG has been found to prevent cell growth and increase apoptosis in renal carcinoma cells, likely due to the fact that it boosts tissue factor pathway inhibitor-2 (TFPI-2) production." (PMID 37838685, 2023).